IFNA2 (interferon alpha 2)
Diseases named in the same sentence as IFNA2 in open-access papers (continued):
Sharing a sentence is not in itself a finding about the gene and the disease.
infection (continued). "WNV, ZKV, and, to a lesser extent, in vivo infection with T. gondii showed the upregulation of many of the genes in this pathway, though differences could be seen even between these three experimental conditions (e.g., Ifna2, 4, 5, 12)." (PMID 40444956, 2025). "In a recent study, we described successful infections of HIL mice with HCV, resulting in the development of HCV-specific human immune responses and clinical symptoms such as liver inflammation and fibrosis by 9 weeks post infection, which, could be ameliorated by treatment with interferon alpha-2a." (PMID 28886065, 2017). "Infection of PCLS resulted in the robust secretion of IFNγ, followed by IFNL1, and IFNα2, while secreted IFNβ was unchanged (IFNγ>>IFNL1> IFNα2>> IFNβ)." (PMID 34899695, 2021). "The synthesis of IFNα1, IFNα2, and IFNβ mRNAs after MOPV infection started as early as eight hours post-infection (hpi), peaked at 24 hpi, and then decreased to reach the level of that of uninfected cells at 40 hpi." (PMID 30419076, 2018). "Our data show that the majority of these genes were induced to higher levels when incubated with conditioned supernatants from late infection, with TLR3 and IFNα-2 being notable exceptions." (PMID 25798928, 2015). "Although clinical administration of IFNα2 increased the number of low-dose mucosal inoculations needed for breakthrough SIV infection in rhesus macaques, once the infection was established, lower CD4 T cell counts were observed in IFNα2-treated monkeys relative to untreated controls." (PMID 33064743, 2020). "Although the IFNA2 signaling pathways were completely abolished, the GS2 cell line exhibited notable elevation in the percentage viral cytopathology that was observed at the early stage of infection following infection with SPDV, EHNV, or VHSV at 15°C." (PMID 31142600, 2019). "Data from African green monkeys suggest no adverse consequences from IFNα2 administration starting 9 days post-infection, although ISGs were not further upregulated." (PMID 27500281, 2016). "To further decipher the role of TRAF6 in the IFN antiviral response, we evaluated HIV-1 replication, 24 hours after infection of IFNα2 pre-treated or not macrophages." (PMID 22140520, 2011). "We therefore examined gene expression for several important interferon-related genes (IFNα2, IFNα4, IFNβ, IFNαβR, IFNγ, IFNγR, Irf3, Irf7, Mx1, Oas1, IFITM1, IFITM2), along with inflammasome-related genes IL-1β and NLRP3, and chemokines CCL5, CCL7, and CCL12 at d1 post-infection." (PMID 26110868, 2015). "After 48 h in culture without infection, hiPSC-derived trophoblasts from both CZS-affected and non-affected twins were able to secrete IFNA2 and IFNG, whereas IFNL1 was not detectable." (PMID 32745093, 2020). "We also quantified in the hiPSC-derived trophoblasts the secreted levels of type I (IFNA2), type II (IFNG) and type III (IFNL1) IFNs produced by these cells in the absence of virus or after infection with ZIKVBR and culture for 48 h or 96 h." (PMID 32745093, 2020). "The release of IFNα2 and TNFα did not mimic virus propagation kinetics as was seen in human MDM, but was a staged response with TNFα appearing early in the infection and IFNα2 increasing at 3–5 dpi." (PMID 27191161, 2016). "The effect of pre-infection IL-2, GROα, IFNα2, and SDF1-α on CD4 decline is likely to be independent of VL and HIV replication and instead may be reflective of pre-infection immune state that is favourable in the context of HIV disease progression once the person is infected." (PMID 35165387, 2022).
cancer (50 papers, 1993 to 2025). A tumor composed of atypical neoplastic, often pleomorphic cells that invade other tissues. "Bender assessed QoL as part of a trial with 16 patients, and showed a significant reduction in physical well-being associated with high-dose interferon alpha-2b therapy using the Functional Assessment of Cancer Therapy – General (FACT-G) scale." (PMID 16449995, 2006). "Among the 14 known IFNα genes, IFNα2A, also called IFNα2 or Roferon-A, is well characterized and has been used in the treatment of viral infections and different kinds of cancers." (PMID 39352890, 2024). "Although the human IFN-I family comprises 16 distinct subtypes, only IFNα2 has been widely explored as an anti-cancer agent." (PMID 36505400, 2022). "Interferon alpha 2 (IFN-α) is the first cytokine to win FDA approval as a single-agent cytokine therapy for cancer in 1986." (PMID 35795050, 2022). "To date, IFNα2 (IFNα2B) remains the only IFNα subtype clinically approved for the treatment of cancer." (PMID 36505400, 2022). "Although it is now apparent that individual IFN-I subtypes display distinct biological activities, only IFNα2 has been used in the clinic to treat cancer." (PMID 36505400, 2022). "Recombinant IFNα2 became the first human immunotherapeutic agent approved by the FDA for RCC cancer treatment." (PMID 34638458, 2021). "IFNα2, like other type I interferons, can inhibit cancer cell proliferation, enhance immune system-mediated cancer cell response, and enhance the efficacy of therapeutic agents." (PMID 34855926, 2021). "To date, only human IFNα2 has been used clinically for the treatment of cancer, with direct comparisons between subtypes rare." (PMID 34552594, 2021). "Multiple studies show that the therapeutic use of IFNα2 with Tα1 in combination is more effective and safer for chronic hepatitis infections as well as various types of cancer due to synergy in their activities." (PMID 34203928, 2021). "Interferon alpha 2b is a potent cytokine and widely used in clinic for antiviral infection and various cancers." (PMID 27110503, 2016). "This mini review focuses on human interferon alpha-2b (hIFNα-2b) as therapeutic protein for cancer treatment." (PMID 24741445, 2014). "Paterson looked at 21 patients receiving high-dose interferon alpha-2b using the Functional Assessment of Cancer Therapy – Biological Response Modifier (FACT-BRM) scale, showing decreased QoL." (PMID 16449995, 2006). "Cisplatin also has a radio-sensitising effect and shares similar properties of cytotoxic synergy with interferon alpha-2b and 5-FU in both experimental and clinical cancer systems." (PMID 15826316, 2005). "Considering their clinical potential and the early successful use of cytokines in cancer immunotherapy, such as interferon alpha-2b (IFNα-2b; IntronA®) and IL-2 (Proleukin®), cytokine-based therapeutics have been extensively evaluated in many follow-up clinical trials." (PMID 37483629, 2023). "In the clinic, only IFNα2 has been a gold standard for cancer treatment." (PMID 32308653, 2020). "Since STAT1 has been shown to promote apoptosis and carry tumor suppressor functions in different types of cancers, the correlation among parameters we reported here will help to explain the mechanism of our developed interferon alpha 2b in the cancer treatment." (PMID 27110503, 2016). "Hu-IFNα2 also drove antiproliferative activity in the HyBNAR expressing mouse cells, but with a decreased potency of two orders of magnitude, which is in line with findings for human cancer cells." (PMID 24416207, 2014). "In two cancer cell lines (CAKI-2; A-498), the protein of IDO and PTEN was measured followed by IDO induction with interferon alpha-2 (IFN-α2)." (PMID 40699758, 2025).
cancer (continued). "Additionally, the increased production of pro-inflammatory cytokines such as IL-1b, IL-6, IFNa2, and TNFa, amongst others, is critical to the development of the host response to foreign microorganisms, the vaccine-based immune response, and the response to cancer immunotherapy." (PMID 33807734, 2021). "Derivatives of IFNα2 have been the focus of most IFN-based therapies, but several studies have explored the effect of IFNβ during various models of cancer." (PMID 33408718, 2020). "Fractalkine, GRO, IFNα2, IFNγ, IL-4, and MDC are also thought to play a role in the development of cancer cachexia." (PMID 30513792, 2018). "Interferon alpha-2a (IFN-alpha) and folinic acid (FA) have been shown to modulate the cytotoxic effects of 5-fluorouracil (5-FU) in the treatment of cancer." (PMID 7819023, 1995). "However, iPSCs alone had little influence on the levels of Sting (Tmem173), Ifnα2 and Ifnβ1, suggesting that radiotherapy promoted type I IFN production via STING to increase the antitumor efficacy of iPSC cancer vaccines." (PMID 38821980, 2024). "With close collaborations between academia and industry, recombinant IFNα2 became the first human immunotherapeutic approved by the US Food and Drug Administration (FDA) for cancer and, other than insulin, the first FDA-approved pharmaceutical product produced by recombinant DNA technology." (PMID 36091125, 2022). "When IFNα2–Tα1 was analyzed for its ability to inhibit the proliferation of cancer cells, it was observed that IFNα2–Tα1 inhibits the proliferation of HepG2 and MDA-MB-231 cells more effectively as compared to reference IFNα2 alone." (PMID 34203928, 2021). "In addition, three interferons (IFNA1, IFNA2, and IFNE) and MIR31HG (microRNA-31 Host Gene) were also in the top 10 for these two cancers." (PMID 32033319, 2020). "5-FU and interferon alpha-2b have been used together to advantage in several cancer settings, but not as part of a combined modality program." (PMID 15826316, 2005). "In addition, the higher ratios of IFNα2 to Th2 cytokines, including IFNα2/IL4, IFNα2/IL10, IFNα2/CCL2, IFNα2/CCL7, IFNα2/CCL11, and IFNα2/TNFα, were associated with increased odds of ER negative vs. ER positive cancer." (PMID 24473087, 2014). "Unlike HMGB1, IFNA1, IFNA2, IL-2, KIR2DL3, IL-13 and NCAPG2 demonstrated an intuitive correlation in only a few cancer types." (PMID 36776838, 2023).
tumor (50 papers, 1992 to 2026). "Initially approved for use in melanoma, IFNα2 was subsequently associated with tumor regression and/or prolonged survival in a diverse hematological and solid malignancies including myeloma, lymphomas, renal cell and bladder carcinomas and Kaposi sarcoma." (PMID 38962090, 2024). "Collectively, these findings provide a strong rationale for future studies aimed at elucidating the underlying mechanisms driving enhanced adaptive anti-tumor protection by IFNα2 and IFNα9." (PMID 32308653, 2020). "We have previously shown that a short course of recombinant interferon-alpha-2b (rIFN-alpha-2b) (3 million units day for 5 days) for patients with primary gynaecologic malignancies was able to increase the circulating levels of a newly discovered tumour associated antigen, termed 90K." (PMID 8439505, 1993). "Clinical trial NCT04830592 uses intravenous infusion to deliver an adenoviral vector producing a bispecific T cell activator (TAc) plus CXCL9/CXCL10/IFNa2 to kill tumor cells and stimulate immunity against the tumor cells." (PMID 41332581, 2025). "IFNα2, expressed by IFNA2, belongs to the IFNα family and is a widely implicated immunomodulatory protein in tumor development." (PMID 38461430, 2024). "We demonstrated the inhibitory effect of IFNA2 on tumor proliferation in both in vivo and in vitro experiments, providing further evidence for the role of IFNA2 in EC." (PMID 38461430, 2024). "The first immunotherapies to become FDA-approved were the anti-tumor cytokines interferon-alpha 2 (IFN-a2) and interleukin-2 (IL-2), molecules that stimulate T-cell proliferation." (PMID 39451258, 2024). "In the flow cytometry assay, the expression of IL-21, IL-27, and IFNA2 proteins with anti-tumor functions were elevated significantly in DBMSCs after treatment with MDA231 cells compared to the untreated DBMSCs." (PMID 39768220, 2024). "Mechanistically, IFNα2 exhibits direct cytotoxicity and anti-proliferative activities on tumor cells." (PMID 39204319, 2024). "Anti-tumor formulation based on recombinant Interferon alpha-2b in the form of microparticles for parenteral administration." (PMID 37688241, 2023). "We show that IFNα2 and IFNα9 are the only subtypes capable of completely controlling tumor outgrowth, with this protection dependent on the presence of an adaptive immune response." (PMID 32308653, 2020). "This, in combination with decreased IFNA2, activated DCs, and altered antigen presentation enables an immune-tolerant environment that allows tumor to evade host recognition." (PMID 33415077, 2020). "In contrast, IFNα2 and IFNα9 were able to completely abrogate tumor growth in a proportion of mice, a phenomenon that was dependent on an intact adaptive immune system." (PMID 32308653, 2020). "This loss of protection against tumor growth in RAGo/o mice suggests an important role for the modulation of the adaptive immune response by IFNα2 and IFNα9 within the local tumor microenvironment." (PMID 32308653, 2020). "The in vitro biological activities, such as anti-tumor activity and antiviral activity of Nova and recombinant human interferon alpha-2b (rhIFN-α2b) was performed; in vivo anti-tumor activity in nude mice was also tested." (PMID 24467885, 2014). "While IFNα2 and other type I interferons showed promising anti-tumor effects, it soon became clear that systemic administration was associated with severe adverse outcomes, including cytopenias, fatigue, anorexia, hepatotoxicity, flu-like symptoms and severe depression with suicidal ideation." (PMID 38962090, 2024). "The tumor image vividly illustrates the inhibitory effects of IFNα2 on tumor growth in vivo." (PMID 38461430, 2024). "The emergence of the tumor stroma as a complex and integral part of the tumor mass resulted in the mid-1980s in the approval of treatments based on targeting the tumor stroma (e.g., 1986 IFNA2 treatment), including today’s immunotherapies." (PMID 37190121, 2023).
tumor (continued). "IFNα2 regulates the expression of multiple interferon regulatory genes (IRGs), and effector proteins of these IRGs directly affect proliferation, differentiation, growth and other functions of tumor cells." (PMID 34203928, 2021). "IFNα2 induces the expression of other cytokines and activates immune cells such as natural killer (NK) cells, macrophages, dendritic cells (DCs), and cytotoxic T cells to regulate immune response, which further generates anti-tumor immunity." (PMID 34203928, 2021). "However, in stark contrast to WT mice, where we observed a proportion of mice failing to develop a palpable tumor, all RAGo/o mice that were challenged with either B16_IFNα2 or B16_IFNα9 developed palpable tumors." (PMID 32308653, 2020). "Why IFNα2 and IFNα9 are able to control tumor growth compared to the other subtypes remains unclear." (PMID 32308653, 2020). "Interestingly, experiments with pegylated IFNα2 combined with docetaxel in mice bearing orthotopic implantations of PC3-MM2 PCa cells resulted in a reduction of tumor weight and increased apoptosis of tumor-associated endothelial cells." (PMID 23913484, 2013). "Instead, patient #5 presented a mTDLN with a low HLA-I tumor expression but a high percentage of CD4+ T cells (44%) and a high number of CD20+ nests in the peritumoral area before treatment with interferon alpha-2b." (PMID 37691949, 2023). "For spleens from tumor bearing old mice majority of the upstream regulators are either interferons (IFNγ, IFNα, IRF3, IRF7, and IFNA2) or are related to the immune system (IKBKB, CHUK, NFκB, NFκBIA, STAT3, and mir-21) and are predicted to be up-regulated." (PMID 26497558, 2015). "Initially, cell attachment assay was performed to determine whether the fusion of Tα1 to IFNα2 affects its binding to the tumor cells or not." (PMID 34203928, 2021). "The application of adjuvant topical interferon alpha-2b in cases with narrow, indeterminate, or negative surgical margins seems to obtain better tumor control than re-excision, incisional biopsy-guided interferon alpha-2b therapy, or empiric interferon alpha-2b treatment as monotherapy." (PMID 34452388, 2021).
infectious disease (3 papers, 2008 to 2022). A disorder directly resulting from the presence and activity of a microbial, viral, or parasitic agent in humans. "With these patient cohorts we sought to test the hypothesis whether the indel polymorphism in the promoter of the IFNA2 gene is associated with disease outcome of other infectious diseases." (PMID 19055755, 2008). "To determine the association of the deletion -305_-300delAACTTT with different infectious diseases, we compared the frequency of IFNA2 with clinical manifestation of the diseases as well as with treatment outcome." (PMID 19055755, 2008).
bacterial infection (2 papers, 2020 to 2021). "Data showed that females exhibit higher levels of anti-viral type 1 interferons IFNA17, IFNA2, IFIT1, IFIT3 and IFNE in the immune tissues/cells, which serve as the first line of defense against viral and bacterial infections." (PMID 33271804, 2020).
peripheral neuropathy (1 paper, 2010). A disorder affecting the peripheral nervous system. "IFNα2 has been reported to induce or exacerbate peripheral neuropathy in patients with HCV-associated mixed cryoglo-bulinemia." (PMID 27713294, 2010).
IFNA2 also shares sentences with these, for which no sentence is quoted: pneumonia (10 papers); influenza (7); ZIKV infection (4); Behcet disease (3); dengue (3); endometriosis (3); HCMV infection (3); hepatitis B (3); periodontitis (3); thymoma (3); adenocarcinoma (2); asthma (2); autoimmune hepatitis (2); delirium (2); depression (2); dermatomyositis (2); encephalitis (2); infertile (2); liver fibrosis (2); lung fibrosis (2); lupus nephritis (2); malaria (2); microcephaly (2); myasthenia gravis (2); oral cancer (2); renal carcinoma (2); viral disease (2); acute leukemia (1); acute liver failure (1); acute myeloid leukemia (1).
A further 94 diseases each share a sentence with IFNA2 in 1 paper.